CDH22 (cadherin 22)
Description:
Cadherins are calcium-dependent cell adhesion proteins. They preferentially interact with themselves in a homophilic manner in connecting cells; cadherins may thus contribute to the sorting of heterogeneous cell types. PB-cadherins may have a role in the morphological organization of pituitary gland and brain tissues (By similarity).
Synonyms: C20orf25; dJ998H6.1
Tractability: Antibody: UniProt places it where antibodies can reach, with medium confidence; UniProt predicts a signal peptide or a membrane-spanning region; its Gene Ontology location is reachable by antibodies, with medium confidence.
Gene: Protein-coding gene on chromosome 20 (46,173,737 to 46,309,009, reverse strand). Ensembl gene ENSG00000149654.
Subcellular location: Cell membrane
Gene Ontology:
Molecular function: beta-catenin binding; cadherin binding; calcium ion binding
Biological process: adherens junction organization; calcium-dependent cell-cell adhesion; cell migration; cell morphogenesis; cell-cell adhesion mediated by cadherin; cell-cell junction assembly; cell adhesion; cell-cell adhesion; homophilic cell-cell adhesion
Cellular component: adherens junction; catenin complex; membrane; plasma membrane
Genetic constraint (gnomAD): Loss-of-function variants: 29 observed, 50.56 expected, observed/expected ratio (o/e) 0.57, 90% interval 0.43 to 0.78. The upper end of that interval is the gene's LOEUF score, 0.78, which puts it in group 3 of 6, group 1 being the genes least tolerant of losing a copy. Missense variants: 1,007 observed, 1,100 expected, observed/expected ratio (o/e) 0.92, 90% interval 0.87 to 0.96. Synonymous variants: 506 observed, 480.72 expected, observed/expected ratio (o/e) 1.05, 90% interval 0.98 to 1.13.
Homologues: Orthologues: chimpanzee CDH22 (99% identical), macaque CDH22 (99% identical), dog CDH22 (97% identical), pig CDH22 (96% identical), mouse Cdh22 (93% identical), rat Cdh22 (88% identical), guinea pig CDH22 (86% identical), tropical clawed frog cdh22 (70% identical), zebrafish cdh22 (63% identical). Paralogues in human: CDH7 (52% identical), CDH20 (50% identical), CDH18 (49% identical), CDH9 (48% identical), CDH10 (48% identical), CDH11 (48% identical), CDH6 (48% identical), CDH8 (47% identical), CDH12 (47% identical), CDH24 (44% identical), CDH19 (41% identical), CDH5 (35% identical), and 21 more.
Diseases named in the same sentence as CDH22 in open-access papers:
CDH22 is named in the same sentence as 20 diseases in open-access papers, as found by Europe PMC text mining. Sharing a sentence is not in itself a finding about the gene and the disease. The quoted sentences say what the papers report.
breast carcinoma (3 papers, 2017 to 2021). "Methylation at many gene promoters has been reported to have independent prognostic value in breast cancer including HOXA11, ESR1 and PITX2, HOXD13 CDH22 BRCA1 and RASSF1." (PMID 33461604, 2021).
schizophrenia (2 papers, 2017 to 2021). A major psychotic disorder characterized by abnormalities in the perception or expression of reality. "Schizophrenia genes relevant to cell adhesion comprised of several members of the cadherin family CDH22, CDH4, CDH7 and CDH9 as well as the protocadherin PCDH10." (PMID 34859219, 2021).
type 2 diabetes (2 papers, 2015 to 2018). "The recent reports suggested that several known SNPs in the CDH22 were associated with type II diabetes and higher BMI." (PMID 25952924, 2015).
dysplastic nevus (1 paper, 2017). Clinically atypical nevi (usually exceeding 5 mm in diameter and having variable pigmentation and ill defined borders) with an increased risk for development of non-familial cutaneous malignant melanoma. "Thus, a lower level of CDH22 protein expression has been reported in metastatic melanoma than in dysplastic nevus." (PMID 28149335, 2017).
inflammatory bowel disease (1 paper, 2014). A spectrum of small and large bowel inflammatory diseases of unknown etiology. "CDH22 is a cadherin protein associated with colorectal cancer disease, while association of ZPBP with inflammatory bowel disease was shown in a previous genome-wide association study." (PMID 25163507, 2014).
Insulin resistance (1 paper, 2024). Increased resistance towards insulin, that is, diminished effectiveness of insulin in reducing blood glucose levels. "The only studies that used this approach so far allowed to discover a differentially methylated site in the fatty acyl CoA reductase 2 (FAR2) gene that was associated with insulin resistance and another site in the cadherin-like 22 (CDH22) gene that was associated with MetS." (PMID 38419113, 2024).
metabolic syndrome (1 paper, 2018). A cluster of metabolic risk factors for CARDIOVASCULAR DISEASES and TYPE 2 DIABETES MELLITUS. "A significant increase in CDH22 gene methylation in subjects with metabolic syndrome was identified in the overall sample." (PMID 29850476, 2018). "The top site, located in the cadherin-like 22 (CDH22) gene, had increased methylation in subjects with metabolic syndrome (i.e., hypermethylation)." (PMID 29850476, 2018).
cancer (5 papers, 2017 to 2024). A tumor composed of atypical neoplastic, often pleomorphic cells that invade other tissues. "In 2017, CDH22 mRNA was identified as a hypoxic eIF4E2 target that encodes cadherin-22, a cell-cell adhesion molecule providing cancer cells with collective migratory and invasive properties specifically in hypoxia." (PMID 29317983, 2017). "Several top-ranking genes, such as MEIS1, ZDHHC11, CWH43, TTC12, and CDH22, have been supported by recent studies as playing roles in various cancers and aging-related processes." (PMID 39499149, 2024). "This study explored the unknown molecular status and clinical value of CDH22 deregulation in BC, which have been described in other cancer types." (PMID 28149335, 2017). "Despite its controversial role, no studies have examined the mechanisms underlying CDH22 deregulation in cancer." (PMID 28149335, 2017). "Cadherin-22, a cell-cell adhesion molecule, is upregulated by promoter eIF4E2-mediated mTORC1-independent translational control during hypoxia; the novel function of cadherin-22 acts as a hypoxia-specific cell surface molecule and is involved in cancer cell migration, invasion, and adhesion." (PMID 36979474, 2023). "Furthermore, CDH22 expression colocalized with hypoxic regions in human glioma and breast cancer patient tumor specimens and high protein levels significantly correlated with tumor size, cancer stage, and progression-free survival." (PMID 29317983, 2017). "Cadherin-22 is a cell-surface molecule target of EIF4E2 and it is involved in cell migration, invasion and adhesion during cancer development." (PMID 33175867, 2020).
tumor (2 papers, 2017). "Five CpG sites in the CDH22 promoter were examined by pyrosequencing in a larger series of 142 BC cases, 26 paired adjacent-to-tumour tissues and 19 non-neoplastic breast samples from reduction mammoplasties." (PMID 28149335, 2017). "We observed by immunohistochemistry that the level of CDH22 expression was lower in BC tissues than in their matched adjacent-to-tumour and non-neoplastic tissues from reduction mammoplasties." (PMID 28149335, 2017).
metabolic disease (1 paper, 2018). A congenital disorder (due to inherited enzyme abnormality) or acquired (due to failure of a metabolically important organ) disorder resulting from an abnormal metabolic process. "Nevertheless, it may be that CDH22 regulation, through both genetic and epigenetic mechanisms, could point to a potentially important role for this gene in metabolic disease." (PMID 29850476, 2018).
CDH22 also shares sentences with these, for which no sentence is quoted: autism (2 papers); colorectal cancer (1); epilepsy (1); glioblastoma (1); KBG syndrome (1); melanoma (1); metastatic melanoma (1); neurological disorders (1); obsessive-compulsive disorder (1); ovarian carcinoma (1).